CRP (C-reactive protein)
Diseases named in the same sentence as CRP in open-access papers (continued):
Sharing a sentence is not in itself a finding about the gene and the disease.
Sepsis (continued). "In a recent randomized controlled trial (RCT) evaluating the therapeutic ability of blood purification (BP) in cases of severe burns with sepsis, researchers assessed the prognosis of serum values of PCT, CRP, and BNP." (PMID 39982339, 2025). "Hematologic ratios are regarded as early markers of inflammation and sepsis in human medicine, with their changes even preceding alterations in acute-phase proteins, such as serum amyloid A (SAA), presepsin, or C-reactive protein." (PMID 40805061, 2025). "First, it provides a comprehensive analysis of multiple inflammatory markers, including CRP, IL-1β, IL-6, IL-8, IL-10, PCT, and TNF-α, which offers a detailed understanding of the immunomodulatory effects of ulinastatin in the treatment of sepsis." (PMID 40667510, 2025). "At present, the clinical diagnosis and evaluation of severe pneumonia complicated with sepsis primarily depend on traditional indicators, such as PCT, CRP, and SOFA scores." (PMID 41293058, 2025). "The LR+ of 6.00 (95% CI, 1.78–20.21) for the CRP test was sufficiently high to serve as a rule-in test, whereas the elevated LR− at 0.23 (95% CI, 0.09–0.61) could not diminish the pretest probability to a level that would allow for the safe exclusion of sepsis." (PMID 40416430, 2025). "In patients without malignancy, PCT demonstrated the best discriminative ability for sepsis, with an AUC of 0.909, followed by MDW (0.883) and CRP (0.823)." (PMID 41303127, 2025). "CRP and PCT are widely used biomarkers for diagnosing and monitoring sepsis; however, both biomarkers have limited specificity." (PMID 40941711, 2025). "Conventional markers like white blood cell count (WBC), C-reactive protein (CRP), and procalcitonin (PCT) have long been used in clinical practice to identify sepsis." (PMID 40870363, 2025). "C-reactive protein and procalcitonin were elevated (CRP: 310 mg/L; PCT: 21.3 ng/mL), suggesting ongoing systemic inflammation and sepsis." (PMID 40861689, 2025). "At the same time, it strongly abated inflammatory factors like CRP and PCT, two important indicators of the progression of sepsis." (PMID 41145817, 2025). "For example, C-reactive protein (CRP) is a widely used biomarker for detecting inflammation and infections, such as bacterial pneumonia or sepsis, in several LIC settings." (PMID 40475767, 2025). "Sepsis screen revealed a white blood cell (WBC) count of 18.16 × 109/L (reference range 7.3-16.6 × 109/L), with CRP trending from 44 mg/L (reference range 0-5 mg/L) initially, to 23 mg/L, 10 mg/L, and <4 mg/L over 10 days." (PMID 41473621, 2025). "Both CRP and PCT are commonly used as indicators of inflammation in clinical practice, as they have predictive value in the development of sepsis." (PMID 40784366, 2025). "Consistent with previous studies, MDW demonstrated superior performance to CRP and comparable or slightly improved accuracy over PCT in diagnosing sepsis." (PMID 41303127, 2025). "Biomarkers such as CRP, PCT, IL-6, IL-8, CD64, and CD11b, are of great significance for early (24‒48 h) diagnosis of neonatal Sepsis and monitoring the effect of antibiotic treatment before bacterial culture detection results." (PMID 40774030, 2025). "This study aims to compare the temporal changes in GDF15 levels with those of classical inflammatory biomarkers, such as CRP, PCT, and P-SEP, in septic patients, exploring its potential role as a biomarker for clinical monitoring in sepsis." (PMID 40941711, 2025). "IL-40 levels were significantly elevated in patients with sepsis upon admission, and were positively correlated with PCT, CRP, lactate and SOFA scores." (PMID 41041682, 2025). "Acute phase reactants, including c-reactive protein (CRP), serum amyloid A-1 (SAA1), and serum amyloid A-2 (SAA2), significantly discriminated sepsis patients from healthy controls." (PMID 40864331, 2025). "C-reactive protein (CRP), procalcitonin (PCT), D-dimer and ferritin had been considered as biomarkers in sepsis." (PMID 39891057, 2025).
Sepsis (continued). "Inflammatory biomarkers such as C-reactive protein (CRP), procalcitonin (PCT), and fibrinogen play a pivotal role in the early diagnosis, monitoring, and prognostic assessment of sepsis." (PMID 41153844, 2025). "Previous studies have mainly focused on individual biomarkers in sepsis, such as PCT, CRP, or sTREM-1, but few have assessed a broader immunological panel within the same patient cohort." (PMID 41153764, 2025). "Although CRP and PCT are commonly used in laboratory testing, they are insufficient on their own for the early diagnosis of sepsis." (PMID 40242671, 2025). "While conventional biomarkers such as C-reactive protein (CRP) and procalcitonin (PCT) have long been used in the clinical management of sepsis, increasing attention has been directed toward hematological inflammation-based indices." (PMID 40722789, 2025). "Patients with severe SARS-CoV-2 infection had comparable levels of C-reactive protein (CRP), interleukin-6 (IL-6), and most types of leukocytes compared to sepsis patients with different disease etiologies." (PMID 41233786, 2025). "The URO-RESIST study aimed to assess the relationship between clinical features, inflammatory biomarkers (C-reactive protein and procalcitonin, CRP and PCT, respectively), microbiological profiles, and outcomes in patients with sepsis with UTI." (PMID 41148729, 2025). "CRP and PCT levels exhibit a significant effect on the development of sepsis in both univariate and multivariate analyses." (PMID 41011807, 2025). "In predicting 28-day mortality in sepsis patients, ACSL4 emerged as a better indicator than traditional infectious markers such as PCT and CRP, though it was less robust than the SOFA score and APACHE II score." (PMID 40264754, 2025). "Although biomarkers such as procalcitonin (PCT), interleukin-6 (IL-6), and C-reactive protein (CRP) have been extensively studied for the diagnosis of infection and sepsis, their clinical performance in immunosuppressed patients remains less clearly defined." (PMID 40428847, 2025). "CRP and PCT are widely used inflammatory markers in sepsis, whose levels are typically significantly elevated during infection and inflammatory responses." (PMID 41346598, 2025). "The included articles contained information regarding neonates who underwent CRP and PCT testing to diagnose neonatal sepsis." (PMID 40970024, 2025). "As a biomarker for infection and sepsis, HBP has been compared to other commonly used biomarkers such as Neutrophil to Lymphocyte Ratio, White Blood Count, C-reactive protein, and Procalcitonin, with at least comparable performance." (PMID 41007875, 2025). "Elevated CRP levels in deceased ICU patients suggest a more severe inflammatory response, potentially due to infections (e.g., sepsis), organ dysfunction, or other critical conditions." (PMID 40407554, 2025). "Short pentraxin CRP and long pentraxin PTX3 are not only sepsis biomarkers but have also been shown to induce the upregulation of cell adhesion molecules on immune cells and trigger complement activation." (PMID 39951217, 2025). "CRP and PCT levels cannot effectively indicate fungal and viral infections, and have limited prognostic value in patients with sepsis." (PMID 41153306, 2025). "Regarding laboratory tests, parameters including N%, IG%, Hb, ALB, TBIL, K, P, Ca, Cr, Cysc, CRP, IgA, APTT, PT, D-dimer, Fib, Lac, PLT, and PCT in the sepsis group were significantly different from those in the non-sepsis group (P < 0.05)." (PMID 40933706, 2025). "In infection and sepsis patients, the proportions above the cutoff values for MDW, CRP, and PCT were 76.0%/91.0%, 94.5%/97.4%, and 48.3%/78.8%, respectively." (PMID 41303127, 2025). "Although previous studies have explored the prognostic value of CRP and PCT in AIDS-related sepsis, our study is the first to examine the CPAR and PAR as composite markers." (PMID 40911630, 2025).
Sepsis (continued). "The prognostic significance of HBP, IL-6, PCT, CRP, Lac, and SOFA for patients diagnosed with severe pneumonia and sepsis." (PMID 41293058, 2025). "First, there is a critical need to develop and validate sepsis biomarkers specific to the ESRD population, given the limitations of conventional indicators such as CRP and procalcitonin in this group." (PMID 41010430, 2025). "In patients with SIRS/sepsis/septic shock, LPC 15:0 negatively correlated with CRP, and all but LPC 18:3, 22:4, 22:5, and 22:6 with procalcitonin." (PMID 41007672, 2025). "Combined measurement of CD64%, hs-CRP, TLC, and ANC achieved the highest F-ratio (24.0) with a highly significant value (p value < 0.001) between sepsis and control groups." (PMID 40224545, 2025). "The primary outcomes assessed were levels of inflammatory markers such as IL-1β, IL-6, IL-8, IL-10, CRP, PCT, and TNF-α, providing a comprehensive overview of the effectiveness of the combined therapy on inflammatory responses in sepsis patients." (PMID 40667510, 2025). "Inflammatory biomarkers CRP and PCT were significantly elevated in patients with sepsis compared to patients with ME at nearly all study days (eTable 1)." (PMID 41360904, 2025). "In this study, the changes in the platelet count and CRP level were the most significant for LOS, whereas the change in the WBC count was more pronounced for the early detection of sepsis." (PMID 40656203, 2025). "Pre-menopausal immunocompetent individuals had higher rates of sepsis, ESR/CRP elevation, dehiscence, post-operative infection, post-operative bleeding, tissue ischemia, seroma formation, and graft complications." (PMID 41001471, 2025). "In conclusion, this study demonstrated that the NRBC count combined with the CRP and PCT levels have value for the diagnosis and prognosis of pediatric sepsis and septic shock." (PMID 40895306, 2025). "While CRP, PCSK9, ox-LDL and inflammatory cytokines are increased in severe sepsis, systemic sLOX-1 levels have, to our knowledge, not been analysed in sepsis." (PMID 39948564, 2025). "Statistical analysis was performed on serum concentrations of CRP, IL-6, IL-1β, TNF-α, IL-10, and PDL1 from healthy individuals and sepsis patients, using a 95% CI." (PMID 40568710, 2025). "Although both have variable sensitivity and specificity, CRP has low accuracy as compared to PCT, which is a more specific biomarker of infection/inflammation and hence can aid clinicians in diagnosing sepsis." (PMID 40351994, 2025). "Although inflammatory markers such as c-reactive protein (CRP) and procalcitonin (PCT) are utilized to predict the severity and prognosis of sepsis, their accuracy and reliability are often the subject of debate." (PMID 40114237, 2025). "In our study, sST2 levels mirrored the trends observed with high-sensitivity C-reactive protein (hs-CRP), with both markers significantly elevated in the acute heart failure (AHF)/sepsis group compared to the AHF or sepsis groups individually." (PMID 40310380, 2025). "While CRP, lactate, PCT, IL-6, and MR-proADM offer distinct advantages for predicting unfavorable short-term outcomes in sepsis, their comparative and/or combined effectiveness in predicting long-term mortality has yet to be fully explored." (PMID 40724799, 2025). "Currently, several biomarkers have been validated for the diagnosis of sepsis, with procalcitonin (PCT) and C-reactive protein (CRP) being among the most extensively utilized." (PMID 41169360, 2025). "In clinical settings, biomarkers, such as C-reactive protein (CRP) and procalcitonin (PCT), have been widely used to identify and prognosticate sepsis patients." (PMID 41225969, 2025). "The significant differences observed in various laboratory indicators, including WBC, neutrophil count, CRP, and PLT, highlight the potential of these parameters as biomarkers for sepsis." (PMID 40755920, 2025).
Sepsis (continued). "As part of a preliminary study we demonstrated that NeoSep-SAA can detect SAA and predict sepsis in an adult population when compared to a quantitative SAA ELISA (calibrated against the WHO SAA IS), CRP and microbiological culture." (PMID 39937751, 2025). "Commonly used sepsis-related markers in clinical practice include white blood cell count (WBC), C-reactive protein (CRP), and procalcitonin (PCT)." (PMID 40065471, 2025). "This meta-analysis demonstrated that ulinastatin significantly reduces mortality and inflammatory markers such as CRP, IL-1β, IL-6, IL-8, IL-10, PCT, and TNF-α in patients with sepsis compared to control group." (PMID 40667510, 2025). "Clinical evidence supports these findings; a sub-analysis of the DESIRE trial showed significantly lower C-reactive protein (CRP) and procalcitonin levels in DEX-treated sepsis patients." (PMID 40115783, 2025). "They identified CRP, PCT, and preprotease (sCD14-ST) as markers with substantial predictive value and as independent predictors of sepsis in children." (PMID 40933706, 2025). "Compared with CRP levels, RETN levels were found to be equally effective in diagnosing sepsis in neonates and children." (PMID 40416430, 2025). "WBC, neutrophil, immature granulocyte values (both absolute value and percent), thrombocyte, PLR, NLR, CRP, PCT, positive blood culture, positive SIRS criteria, and sepsis were found significantly higher in patients with bacterially caused acute exacerbation." (PMID 40917823, 2025). "The ESR reflects the overall burden of systemic inflammation rather than rapid acute-phase changes and thus is frequently used alongside acute-phase markers such as CRP and WBC counts, particularly in critical care settings like sepsis or SIRS." (PMID 41514728, 2025). "CRP and PCT are important prognostic markers for sepsis and ARDS, and changes in their levels can reflect the severity of the disease and the therapeutic effect." (PMID 40842872, 2025). "CRP and PCT are the pro-inflammatory biomarkers for evaluating the severity of sepsis, while D-dimers is considered a thrombotic biomarker for accessing the progression of CS." (PMID 39891057, 2025). "CRP is a well-established marker of acute inflammation, while PCT is highly specific for bacterial infections and sepsis." (PMID 41438699, 2025). "The granule biogenesis pathway genes CEACAM4, PLAC8, and CD63 were analyzed by quantitative real-time polymerase chain reaction (qRT-PCR) and their abilities to distinguish sepsis and SIRS were compared to the routine infection marker CRP (C-reactive protein)." (PMID 39434093, 2024). "The findings of this study align with and build upon previous research on the prognostic significance of CRP, PCT, and other clinical markers in sepsis." (PMID 39469363, 2024). "Nowadays, traditional biomarkers such as CRP, PCT and IL-6 are widely used in the diagnosis and evaluation of sepsis." (PMID 39371337, 2024). "In another study, it was found that serum levels of nCD64, PCT, CRP, and WBC were significantly higher in the neonatal sepsis group compared to the non-sepsis group (p<0.001)." (PMID 39193501, 2024). "Our research showed that MT-ND6 and ANXA1 were more effective in the short-term prognosis of sepsis than commonly used laboratory markers like PCT, CRP, IL-6 and HBP." (PMID 39611143, 2024). "This study seeks to emphasize the potential of biomarkers, including IL-10, CRP, and PCT, in enhancing the early diagnosis and prediction of sepsis severity in patients." (PMID 39507174, 2024). "Specifically, the role of the CRP and PCT during the course of a sepsis or septic shock, stratified by disease progression or clinical improvement has not yet been investigated." (PMID 37204560, 2024). "Elevated NLR, CRP, and PCT are well-known traditional biomarkers that have long been used in the suspicion of sepsis." (PMID 39336599, 2024).
Sepsis (continued). "In contrast, CRP and PCT are more suited for monitoring disease progression, underscoring the importance of a multifaceted approach to sepsis management that incorporates both early prognostic markers and ongoing monitoring of clinical dynamics." (PMID 39655134, 2024). "Although the accuracy for detecting sepsis is comparable to CRP and PCT in most studies, PSP and MDW hold several advantages over CRP and PCT." (PMID 38831992, 2024). "A BSA@graphene-modified gold electrode achieved multiplexed and simultaneous diagnosis of sepsis biomarkers using PCT and CRP." (PMID 38920613, 2024). "The CRP/albumin-ratio (CAR) has already been investigated as an outcome predictor in various diseases, like sepsis, cancer, cardiovascular diseases, stroke, and intracerebral hemorrhage." (PMID 38791046, 2024). "CRP and PCT are better indicators of sepsis when serial measurements are taken and/or a combination of biomarkers are taken into account with a correlation of their values and trends with clinical findings." (PMID 39858292, 2024). "Currently, the diagnosis of sepsis is mainly based on blood culture, and white blood cell (WBC) count, classification, C-reactive protein (CRP), and procalcitonin precursor (PCT) are determined for auxiliary diagnosis." (PMID 39371337, 2024). "Another study demonstrated that the nCD64 index combined with CRP was superior to CRP, PCT, the nCD64 index, and the nCD64 index plus PCT in predicting the 28-day mortality in sepsis." (PMID 39201697, 2024). "Currently, the most important markers for sepsis diagnosis are procalcitonin (PCT) and C-reactive protein (CRP), which reflect the severity of the infection and can help in treatment decisions." (PMID 38337856, 2024). "Limited data regarding the prognostic value of CRP and PCT during the course of sepsis or septic shock is available." (PMID 37204560, 2024). "The neonate's presentation, including symptoms such as abdominal distension and vomiting, along with laboratory findings of strongly positive C-reactive protein (CRP) and initial management steps, suggested a critical case of suspected late-onset sepsis." (PMID 39364489, 2024). "Our study similarly discovered that the predictive capabilities of CRP and PCT for early sepsis were constrained." (PMID 39212218, 2024). "CRP, PCT and PSP are three biomarkers that have shown promise in the diagnosis and prognostication of sepsis." (PMID 39416748, 2024). "We observed strong correlations of plasma GDF15 levels with the levels of C-reactive protein (CRP), procalcitonin (PCT), lactate dehydrogenase (LDH), and lactate as well as Sequential Organ Failure Assessment (SOFA) scores in patients with sepsis." (PMID 38725041, 2024). "To further indicate the role of plasma CRISP3 in sepsis, we explored the relationships between plasma CRISP3 and SOFA, APACHE II scores, procalcitonin (PCT), and C-reactive protein (CRP)." (PMID 39624089, 2024). "Background and Objectives: The predictive value of changes in C-reactive protein (CRP), procalcitonin, and leukocyte levels, which are commonly used in the diagnosis of infection in sepsis and septic shock, remains a topic of debate." (PMID 39459346, 2024). "Studies have revealed that elevated levels of CRP and PCT are indicative of poor outcomes in patients with sepsis." (PMID 39113822, 2024). "Routine sepsis markers, such as white blood cell count (WBC) and C-reactive protein (CRP), lack specificity." (PMID 38667467, 2024). "The use of biomarkers like procalcitonin (PCT) and C-reactive protein (CRP) in the diagnosis and prognosis of sepsis has demonstrated encouraging results." (PMID 39469363, 2024). "Frequently used biomarkers, such as the total white blood cells, neutrophil count and C-reactive protein (CRP), lack the specificity to discriminate between SIRS and sepsis." (PMID 38792824, 2024). "The AUC of MDW combined with WBC was similar to CRP alone (0.85 [0.83–0.87]) and surpassed that of PCT in diagnosing sepsis." (PMID 39852198, 2024).